CHGA (chromogranin A)
Diseases named in the same sentence as CHGA in open-access papers (continued):
Sharing a sentence is not in itself a finding about the gene and the disease.
small cell carcinoma (21 papers, 2012 to 2025). A neuroendocrine carcinoma composed of small malignant cells which are often said to resemble "oat cells" under the microscope. "Neuroendocrine malignancies, such as small cell carcinoma, are characterised by distinctive biomarkers, including chromogranin A (CgA) and synaptophysin." (PMID 38149143, 2023). "Meanwhile, the patients with small-cell carcinoma had positive immunohistochemical staining for Syn, chromogranin A, neuron-specific enolase, Ki-67, CEA, and P16." (PMID 34711665, 2021). "Biopsy was done and the pathology confirmed small cell carcinoma, strongly positive for cytokeratin (AE1/AE3) and insulinoma-associated protein 1 (INSM-1), scatteredly positive for chromogranin A, synaptophysin and CD56." (PMID 34477164, 2021). "Small-cell carcinomas and high-grade squamous cell carcinomas must be, due to the different clinical features, differentiated by neuroendocrine markers (synaptophysin/chromogranin A) and a squamous-basal marker (e.g., p40) expression." (PMID 32556556, 2021). "The green part showed a grade III hepatocellular carcinoma with an immunoreaction to Hep Par 1, glypican 3 and α-fetoprotein, whereas the white part exhibited a small cell carcinoma, as evidenced by expressions of chromogranin A and synaptophysin." (PMID 28834900, 2017). "The patient underwent surgery, and the pathological diagnosis was small cell carcinoma due to the presence of the typical features of small round cells with scant cytoplasm that were positive for synaptophysin and chromogranin A in the resected specimen." (PMID 24099520, 2013). "The true incidence is probably underestimated, as it may occasionally be misdiagnosed as small cell carcinoma due to their similar morphology and occasional expression of neuroendocrine markers such as synaptophysin and chromogranin A." (PMID 40255709, 2025). "These phenotypically similar, small cell neuroendocrine cancers (SCNCs) are classified as high-grade, poorly differentiated small cell carcinomas that commonly express neuroendocrine markers like chromogranin A (CHGA), neural cell adhesion molecule 1 (NCAM1), and synaptophysin (SYP)." (PMID 39589879, 2024). "Chromogranin A, CD56, and synaptophysin are immunohistochemical markers that are useful in the diagnosis and a low Ki-67 proliferation index (<1%) facilitates differentiation from small-cell carcinoma." (PMID 35685600, 2022). "Concerning the diagnostic aspect, the morphology of tumor cells and other immunhistochemical markers, such as chromogranin A, neuro-specific enolase (NSE), CD57 or CD56, are sufficient to enable the diagnosis of small cell cancer with neuroendocrine differentiation." (PMID 25889870, 2015). "Chromogranin A, CD56 and synaptophysin are the most useful neuroendocrine immunohistochemical markers, and low levels of Ki-67 can help to distinguish neuroendocrine from small-cell carcinoma." (PMID 23760790, 2013). "Furthermore, chromogranin A, CD56, and synaptophysin, are immunohistochemical markers typically expressed in small cell neuroendocrine carcinomas of the lung." (PMID 23536778, 2013). "Immunohistochemical investigation was positive for Synaptophysin and CD56, negative for Chromogranin A and Neuron Specific Enolase (NSE) and was consistent with the diagnosis of metastasis of NEC/small cell carcinoma with Ki-67 90% as additional poor prognostic factor." (PMID 32293342, 2020).
pancreatic neuroendocrine tumor (19 papers, 2014 to 2025). Pancreatic endocrine tumor, also known as pancreatic neuroendocrine tumor (PNET), describes a group of endocrine tumors originating in the pancreas that are usually indolent and benign, but may have the potential to be malignant. "The phase II trial RADIANT-1 showed that elevated baseline chromogranin A in patients with advanced pancreatic NETs who received everolimus was associated with poor outcome." (PMID 34110489, 2022). "In patients with multiple endocrine neoplasia type 1 (MEN1) followed up at ENETS centers of Excellence, chromogranin A (CgA) and pancreatic polypeptide (PP) are widely used screening tools for pancreatic neuroendocrine tumors (panNETs)." (PMID 40455177, 2025). "Both serotonin and chromogranin A are known tumor markers secreted by pancreatic neuroendocrine tumors." (PMID 37007151, 2023). "The tumor manifested several features that were consistent with pancreatic neuroendocrine tumors (panNETs), such as organoid structures with trabecular and cribriform patterns, and the expression of chromogranin A and synaptophysin." (PMID 26192435, 2015). "CHGA has been approved as a powerful biomarker for the early detection of various digestive system carcinomas, including gastric cancer, pancreatic neuroendocrine tumors, and colorectal cancer." (PMID 34322151, 2021). "CHGA and SYP are regarded as markers of NE differentiation structurally linked to cytoplasmic granules and vesicles and are, as a rule, simultaneously expressed in typical NETs of different organs such as pheocromocytomas, intestinal and lung carcinoids and pancreatic NETs." (PMID 24277232, 2014). "In contrast, in patients with pancreatic NET there was a very strong negative correlation of preoperative chromogranin A with GLO1 copy number in primary tumour tissue (r = - 0.94, p = 0.005)." (PMID 29100361, 2017). "Case report: We presented the case of 59-year-old patient, diagnosed with non-functional well-differentiated pancreatic neuroendocrine tumor grade II (NET G2) with the presence of chromogranin A, synaptophysin and somatostatin receptor 2, together with liver and bone metastases." (PMID 27928440, 2016). "Histopathological and immunohistochemical results diagnosed well-differentiated pancreatic neuroendocrine tumor grade II (NETG2) with liver metastases and no spleen invasion, with the presence of diffuse positive chromogranin A and synaptophysin." (PMID 27928440, 2016).
diabetes (16 papers, 2013 to 2026). "Chromogranin A (CgA), B (CgB), and C (CgC), the family members of the granin glycoproteins, are associated with diabetes." (PMID 34204153, 2021). "Few data were reported to date for chromogranin-A, an antigen only recently identified as being associated with diabetes." (PMID 25140192, 2013). "For example, diabetes is suppressed with administration of a plasmid encoding ChgA, IGRP, GAD65 and insulin antigens, and targeting DβH233-241, ZnT8158-166, ZnT8282-290 and proinsulin with a plasmid approach provides better disease protection than proinsulin alone." (PMID 39211046, 2024). "Taking advantage of the Chromogranin A (CgA) knockout (CgA-KO) mouse as a model for healthy aging, we have identified Vsig4 (V-set and immunoglobulin domain containing 4) as the critical checkpoint gene in offsetting age-associated hypertension and diabetes." (PMID 36440192, 2022). "In diabetes, CHGA is regarded as one of the biomarkers and is considered a key regulatory gene related to the development and regulation of diabetes in many studies." (PMID 41372957, 2025). "Chromogranin A, has anti‐inflammatory properties and participates in inflammatory reaction, involves in the pathogenesis of diabetes." (PMID 37249284, 2023). "The current study examined the pro-hormone Chromogranin A (CgA), as this protein regulates both hypertension and diabetes." (PMID 36440192, 2022). "In addition, CHGA, CHGB, SCG2, and some CHGA cleavage products affect glucose homeostasis and different types of diabetes." (PMID 37249284, 2023). "Increased chromogranin A expression has also been reported in patients with type 1 diabetes and it correlates with increased plasma catecholamine levels during the early stages of diabetes." (PMID 37072781, 2023). "The reduction of AMA in prevalent diabetes and a negative correlation of AMA to the glucose level are in a good agreement with present literature data suggesting impaired Chromogranin A amidation in diabetes, thus reducing insulin granule packaging and secretion." (PMID 34349173, 2021). "Also unexpected was the relatively low number of epitopes related to chromogranin-A, recently identified as a diabetes-related auto antigen, exclusively in the NOD mouse." (PMID 25140192, 2013). "In specific mouse models of diabetes, NOD (non-obese diabetic) mice with CHGA gene knockout did not develop diabetes." (PMID 40370467, 2025). "Increased frequency of chromogranin-A-positive/hormone-negative cells has been documented in the pancreas of rodent models with diabetes, in donors with T1D and T2D, as well as in human pancreatic tissues derived from donors affected by pancreatitis." (PMID 35359976, 2022). "Lack of CgA-derived autoantigens in CHGA gene knockout NOD mice, however, may not be the only mechanism protecting from diabetes." (PMID 40370467, 2025).
Hypertension (16 papers, 2011 to 2025). The presence of chronic increased pressure in the systemic arterial system. "Several population studies have reported associations between CHGA genetic variants and susceptibility to age-related diseases such as hypertension, coronary artery disease, heart failure, and metabolic dysfunctions." (PMID 41018225, 2025). "Given their diverse biological functions, CHGA and its derived peptides have been implicated in a wide array of diseases, including cardiovascular conditions, hypertension, type 2 diabetes, cancer, and chronic inflammatory disorders." (PMID 41018225, 2025). "The miR-22 expression is elevated in spontaneously hypertensive rats, reducing the expression of chromogranin A (CHGA), resulting in higher central and peripheral nerve activity, contributing to the pathogenesis of hypertension." (PMID 38345042, 2024). "For example, in hypertension, the plasma concentration of chromogranin A is increased, while the catestatin plasma concentration is decreased." (PMID 34647168, 2021). "As part of biochemical investigations, apart from measuring catecholamines levels, which were normal in our cohort of patients even with hypertension, the tumor marker Chromogranin A was also analysed." (PMID 35054195, 2021). "CHGA is also a candidate gene that contributes to autonomic dysfunction syndromes, including the intermediate phenotypes that contribute to hypertension." (PMID 25887185, 2015). "The inverse relationship between ChgA and catestatin in hypertension might be explained by reduced ChgA to catestatin conversion." (PMID 34944578, 2021). "Furthermore, plasma levels of the catestatin precursor ChgA were two-fold higher in patients with essential hypertension when compared to normotensive counterparts." (PMID 34944578, 2021). "Chromogranin A was shown to regulate vascular homeostasis and the tension of the heart in humans, and increased concentrations are correlated with essential hypertension." (PMID 32704984, 2020). "Interestingly, this is reminiscent of the recent findings on chromogranin A gene knockout mice, which displayed severe hypertension but unaltered plasma cholesterol level as compared to wild type mice." (PMID 21304971, 2011). "Furthermore, patients with essential hypertension and left ventricular hypertrophy, as determined by echocardiography, had a significantly lower catestatin-to-norepinephrine ratio, while mice with ablated ChgA gene showed increased LV mass and LV cavity dimensions." (PMID 31366074, 2019). "Chromogranin A (CHGA), a secretory protein localized primarily in the secretory granules of the neuronal and neuroendocrine systems, is a key molecular player in the pathogenesis of hypertension." (PMID 39585243, 2024). "The immunophenotype (chromogranin A- and S100-) and the absence of hypertension in the patient’s history ruled out a diagnosis of oncocytic paraganglioma." (PMID 27094262, 2016).
colorectal cancer (14 papers, 2012 to 2026). A primary or metastatic malignant neoplasm that affects the colon or rectum. "Brachyury was previously associated with the NE marker CHGA, in colorectal cancer, distinguishing a specific subpopulation of stem cells." (PMID 27049720, 2016). "On the other hand, colorectal carcinoma with neuroendocrine differentiation is also a unique subtype of colorectal carcinomas showing expression of at least one distinctive marker among chromogranin A, synaptophysin, and CD56." (PMID 36434637, 2022). "In the present study, firstly we predicted that CHGA could be a biomarker for colon cancer based on the protein–protein interaction network of all the reported biomarkers that were collected from our colorectal cancer biomarker database (CBD)." (PMID 35681650, 2022). "Several factors are known to affect colorectal cancer (CRC) patient survival, including elevated platelet counts (thrombocytosis) and chromogranin A-positive neuroendocrine-cell differentiation (CgA+)." (PMID 33383764, 2020). "Human chromogranin-A (CHGA) is a 439-residue-long protein found in the secretory granules of some normal and neoplastic neuroendocrine cells, the expression of which is related to the prognosis of colorectal cancer." (PMID 32457797, 2020).
metastatic disease (14 papers, 2015 to 2025). "Adjusted multiple linear regression showed that age, Charlson CMI, presence of metastatic disease, chromogranin A above reference range, and BMI were independently associated with at least one of the outcome variables with significance level p < 0.1." (PMID 33969447, 2021). "Immunostaining showed that intestinal cancer markers (MUC2 and CHGA) and proliferation marker (Ki67) were highly expressed in metastatic tumors derived from orthotopic PDX liver cancers established with Liver ECM." (PMID 40852642, 2025). "The correlation between bowel symptoms and HRQoL was analysed using multiple linear regression, adjusting for age, Charlson Comorbidity Index score, presence of metastatic disease, chromogranin A, and BMI yielding ß-coefficients with 95% confidence intervals." (PMID 33969447, 2021). "Expression patterns of chromogranin A and vascular endothelial growth factor in the metastatic tumors were similar to those observed in pancreatic tumors." (PMID 26192435, 2015). "Nevertheless, the expression of calcitonin and chromogranin A ruled out the possibility of metastatic disease in this marmoset." (PMID 41320889, 2025). "According to the NCCN guidelines, monitoring lab values such as chromogranin A and 5-HIAA every three to six months may be indicated for detecting metastatic disease post-tumor removal." (PMID 38813319, 2024). "Increased serum chromogranin A levels and/or 18-FDG PET scans demonstrating avid uptake in the small intestine performed at an earlier stage would have suggested a different diagnosis of metastatic disease." (PMID 25810937, 2015).
melanoma (13 papers, 2012 to 2026). A malignant, usually aggressive tumor composed of atypical, neoplastic melanocytes. "Catestatin (CST), a Chromogranin A (CgA)–derived peptide with immunomodulatory and reparative properties, has been implicated in tissue protection, but its role in melanoma remains unknown." (PMID 41279995, 2025). "The expression and role of CST, a Chromogranin A (CgA)-derived peptide with immunomodulatory and reparative properties in skin injury led us to examine its connection to melanoma." (PMID 41646326, 2026). "We retrospectively analyzed the expression of chromogranin A (CgA), synaptophysin (Syn) and CD56 as neuroendocrine markers in 308 cases with melanomas." (PMID 34454530, 2021). "The tumor cells were positive for AE1/AE3, S-100 protein, melan A, HMB-45, synaptophysin, calcitonin, chromogranin A, melanoma, and thyroid transcription factor-1 (TTF-1) and negative for thyroglobulin." (PMID 30424779, 2018). "Moreover, since Chromogranin A yields several bioactive fragments—Pancreastatin68, Vasostatin I/II69, WE1470, and Serpinin71—systematic studies of their processing and interactions in melanoma may reveal complementary or cooperative functions." (PMID 41279995, 2025). "An autopsy revealed multiple organ tumors (brain, duodenum, stomach, liver, and bile duct) negative for melanoma markers but positive for neuroendocrine markers (CD56, synaptophysin, and chromogranin A)." (PMID 39192931, 2024). "However, these tumors were also completely negative for melanoma markers, S-100, melan-A, and HMB-45, but positive for neuroendocrine tumor markers, CD56, synaptophysin, and chromogranin A." (PMID 39192931, 2024). "All other markers tested were negative (pan-melanoma, HMB45, Melan A, keratin AE1/AE3, desmin, alpha smooth muscle actin, h-caldesmon, CD34, p16, CD117, DOG1, myogenin, CD10, estrogen receptor (ER), progesterone receptor (PR), PAX8, WT1, synaptophysin, chromogranin A, CD99 and PRAME))." (PMID 39196362, 2024).
small cell lung carcinoma (13 papers, 1993 to 2025). Small cell lung cancer (SCLC) is a highly aggressive malignant neoplasm, accounting for 10-15% of lung cancer cases, characterized byrapid growth, and early metastasis. "Both pathological and immunohistochemical examinations (thyroid transcription factor-1, synaptophysin, and chromogranin A staining) led to the diagnosis of ovarian metastasis of small-cell lung carcinoma." (PMID 31218185, 2019). "Similar to the neuroendocrine subtype of small cell lung cancers, these tumors also displayed upregulation of the neuroendocrine markers chromogranin A and chromogranin B, leading us to name this cluster the neuroendocrine subtype." (PMID 26776158, 2016). "ASCL1 and CHGA have the same overexpression profile in small-cell lung cancer." (PMID 24360028, 2013). "Gfi-1 co-expression with neuroendocrine markers, including the DCV-related protein chromogranin A and calcitonin peptide, in small cell lung carcinoma (SCLC) strongly suggests its involvement in the maintenance of the neoplastic phenotype of neuroendocrine lung tumors." (PMID 19343207, 2009). "Neuroendocrine SCLC cells typically express markers such as chromogranin A, synaptophysin, and CD56 antigen, which are routinely assessed in the immunohistochemical diagnostics of small-cell lung cancer." (PMID 38673793, 2024). "Pathologic examination of the pulmonary specimen of the RUL bronchus revealed small cell lung cancer (SCLC), which was positive for chromogranin-A and negative for CD45." (PMID 20427942, 2010).